MIR628 (microRNA 628)
Synonyms: hsa-mir-628; MIRN628; mir-628
Gene: MicroRNA gene on chromosome 15 (55,372,940 to 55,373,034, reverse strand). Ensembl gene ENSG00000283891.
Gene Ontology:
Biological process: miRNA-mediated post-transcriptional gene silencing
Cellular component: RISC complex
Homologues: Orthologues: chimpanzee ptr-mir-628 (100% identical), macaque mml-mir-628 (99% identical), mouse Gm56102 (83% identical), pig ssc-mir-628 (82% identical), rat Mir628 (79% identical), rabbit MIR628 (61% identical).